AQP5 (aquaporin 5)
Diseases named in the same sentence as AQP5 in open-access papers (continued):
Sharing a sentence is not in itself a finding about the gene and the disease.
gastritis (3 papers, 2016 to 2023). Inflammation of the stomach. "Taken together, the key findings of the present study demonstrate that H. pylori infection activated WNT/β-catenin signaling pathway by upregulating ASCL1/AQP5 to induce gastritis." (PMID 35538066, 2022). "Data obtained in our study elaborated that H. pylori infection facilitated inflammatory response and apoptosis of GECs to promote gastritis through the activation of AQP5/ASCL1/WNT/β-catenin axis." (PMID 35538066, 2022). "AQP5−/− mice were infected with H. pylori WT to assess the role of AQP5 in H. pylori-induced gastritis." (PMID 35538066, 2022). "Gastritis mouse models were established by H. pylori infection, followed by determination of AQP5 and ASCL1 in gastric mucosa." (PMID 35538066, 2022). "As per differential analysis results of GSE106656, ASCL1 was highly expressed in IM patients in contrast to gastritis patients, and was positively correlated with AQP5 expression." (PMID 35538066, 2022). "Therefore, the purpose of this study is to evaluate the mechanistic significance of ASCL1 and AQP5 in H. pylori infection of gastritis." (PMID 35538066, 2022). "Moreover, further mechanistic investigation data in this study unraveled that H. pylori induced AQP5 expression by upregulating ASCL1 that was highly expressed in gastritis." (PMID 35538066, 2022). "Therefore, AQP5 knockout suppressed neutrophil infiltration and apoptosis in mouse gastric mucosa, thereby alleviating H. pylori-induced gastritis." (PMID 35538066, 2022). "Similarly, a published work has also revealed that AQP5 expression elevates in GECs in gastritis, which is related with the H. pylori infection." (PMID 35538066, 2022). "Besides, the effects of AQP5 on H. pylori-induced gastritis were explored using AQP5−/− mice." (PMID 35538066, 2022). "Through the differential analysis of H. pylori infection-induced gastritis-related microarray data GSE106656, we found that AQP5 was significantly overexpressed in intestinal metaplasia (IM) patients compared with gastritis patients." (PMID 35538066, 2022). "These evidences support that H. pylori infection triggered the inflammatory response and apoptosis of GECs to induce the occurrence of gastritis by activating Wnt/β-catenin pathway via upregulation of ASCL1 and AQP5." (PMID 35538066, 2022). "In this context, our study was performed to delineate the involvement of AQP5 and ASCL1 in H. pylori infection during gastritis." (PMID 35538066, 2022). "It is interesting to note that H. pylori infection could elevate Aquaporin 5 (AQP5) expression in gastric epithelial cells (GECs), which promotes the development of gastritis." (PMID 35538066, 2022). "Collectively, these results indicate that the expression of several subtypes of AQPs (AQP1, AQP3, AQP4, AQP5, AQP7 and AQP11) is upregulated by gastritis, and more studies are essential to investigate their potentials as diagnostic biomarkers and drug targets for gastritis therapy." (PMID 27589719, 2016). "Moreover, it was found that silencing of AQP5 could restrain levels of inflammatory factor (TNF-α and IL-1β) and apoptosis of GECs in mice with H. pylori-related gastritis." (PMID 35538066, 2022). "However, the translation of the finding into clinical scenario may be limited by the lack of verification of the expression and distribution of AQP5 and ASCL1 in clinical samples of gastritis and IM, which should be further studied in future investigations." (PMID 35538066, 2022).
ischemia (3 papers, 2022 to 2024). A hypoperfusion of the BLOOD through an organ or tissue caused by a PATHOLOGIC CONSTRICTION or obstruction of its BLOOD VESSELS, or an absence of BLOOD CIRCULATION. "In this study, authors demonstrated that AQP5 expression was downregulated under ischemia injury but was upregulated after scratch-wound injury." (PMID 35884950, 2022). "AQP5 has been detected in primary cultures of astrocytes and neurons and also in rat brain in normal, ischemia, and traumatic injured conditions." (PMID 35884950, 2022). "AQP5 mRNA was shown to be downregulated in rat astrocytes after hypoxia treatment, and similar decreases in AQP5 expression but with concomitant increases in AQP4 expression were observed in an in vitro ischemia model of primary astrocyte cultures." (PMID 36010640, 2022).
keratoconus (3 papers, 2008 to 2025). A degenerative, structural disorder of the eye, characterized by a cone-shaped protrusion of the cornea. "A study which found decreased expression levels of AQP5 in the corneal epithelium of affected patients suggested that AQP5 loss of function may perform a role in the pathophysiology of keratoconus." (PMID 39420106, 2025).
prostate carcinoma (3 papers, 2014 to 2023). A carcinoma that arises from epithelial cells of the prostate gland. "In another study, researchers measured AQP5 expression in prostate cancer tissues and cell lines and established its expression is highly correlative with tumor (T), nodes (N), and metastases (M) (TNM) stage." (PMID 36672280, 2023). "Research investigations found that AQP1 and AQP5 can serve as prognostic biomarker(s) in prostate cancer." (PMID 36672280, 2023). "The study revealed lower expression of AQP5 in normal prostate epithelium, whereas in prostate cancer, its expression showed a dichotomous pattern." (PMID 36672280, 2023). "In prostate cancer, AQP5 expression has been correlated with tumor grade, circulating tumor cells, lymph node metastasis, Gleason score, and PSA." (PMID 35619903, 2022). "To examine the expression status of AQP5 in prostate cancer, we first used immunohistochemical evaluation." (PMID 25217331, 2014). "Over-expression of AQP5 protein was also found in prostate cancer cells and cell proliferation and migration were significantly attenuated by AQP5-siRNA." (PMID 25217331, 2014). "Our results revealed that AQP5 is up-regulated in prostate cancer and this expression is accompanied by AQP5 DNA amplification." (PMID 25217331, 2014). "In the present study, we aimed to determine the clinical significance of AQP5 expression in prostate cancer patients." (PMID 25217331, 2014). "In order to determine the prognostic value of AQP5 for prostate cancer, we analyzed the cumulative survival of patients according to their AQP5 status." (PMID 25217331, 2014). "We first analyzed the correlations between the expression of AQP5 and clinicopathologic features, CTCs, and prognosis of prostate cancer." (PMID 25217331, 2014). "AQP5 expression was measured in 60 prostate cancer tissues and cells (both PC-3 and LNCaP) by immunohistochemistry and immunofluorescence assay." (PMID 25217331, 2014). "Furthermore, another research group attempted to propose AQP5 as a prognostic biomarker by evaluating AQP5 expression in 60 prostate cancer specimens and prostate cancer cell lines." (PMID 36672280, 2023). "AQP5 protein was also expressed in prostate cancer cell lines, PC-3 and LNCaP." (PMID 25217331, 2014). "In addition, in the present study, we also demonstrated significantly decreased cell proliferation and migration of prostate cancer cells with AQP5 silencing." (PMID 25217331, 2014). "The aim of the present study is to elucidate whether the expression of AQP5 is a strong prognostic biomarker for prostate cancer, and the potential role in the progression of prostate cancer cells." (PMID 25217331, 2014). "We concluded that AQP5 in prostate cancer was an independent prognostic indicator." (PMID 25217331, 2014). "Furthermore, we determined that high levels of expression of AQP5 were correlated with gene amplification in our limited cases study, which is the first reported in prostate cancer." (PMID 25217331, 2014). "Although the mechanisms require further elucidation, AQP5 might be used as a novel biomarker for prostate cancer aggressiveness." (PMID 25217331, 2014). "Immunoblotting analysis revealed that both prostate cancer cell lines express AQP5 protein." (PMID 25217331, 2014). "Our results showed that AQP5 was mainly expressed in prostate cancer cells." (PMID 25217331, 2014). "The clinical significance of AQP5 in prostate cancer remains largely unexplored." (PMID 25217331, 2014). "However, the expression of AQP5 in prostate cancer and its clinical significance remain unexplored." (PMID 25217331, 2014). "These conclusions suggest that AQP5 may be an effective therapeutic target for prostate cancer." (PMID 25217331, 2014). "OncoPrint data analysis of prostate cancer patients further uncovers the possibilities of AQP1, AQP3, AQP5 and AQP9 being developed as prognostic biomarkers for prostate cancer." (PMID 36672280, 2023).
prostate carcinoma (continued). "Furthermore, a progressive decrease in the expression of AQP5 and AQP9 was observed during prostate cancer progression that negatively correlates with their expression." (PMID 36672280, 2023). "Even though AQPs including AQP1, AQP3, AQP5 and AQP9 have exhibited significant roles that contribute to prostate cancer prognosis, very little progress has been made in identifying AQPs as biomarker(s) for their use in prostate cancer." (PMID 36672280, 2023). "Studies on structural and functional assessment highlight a strong biological relationship between AQPs protein expression, localization, and key biological functions in normal and prostate cancer tissues, where aberrant AQP1, AQP3 and AQP5 expression correlate with tumorigenesis and metastasis." (PMID 36672280, 2023). "A positive correlation between circulating tumor cells and negative cumulative survival rate was observed with AQP5 expression in prostate cancer patients." (PMID 36672280, 2023). "CTCs were detected in 65.00% (13/20) of prostate cancer patients with strong AQP5 expression versus 30.00% (12/40) with low and absent AQP5 expression (P < 0.05)." (PMID 25217331, 2014). "AQP5 positivity was observed in ERG-positive (15.5%), ERG-negative (5.8%), with PTEN deletion (14.7%) and without PTEN deletion (9.4%) prostate cancers." (PMID 36672280, 2023).
pulmonary diseases (3 papers, 2022 to 2024). "Corticosteroids upregulated Aqp5 mRNA and AQP5 protein expression in adenocarcinomic human alveolar basal epithelial cells (A549) and may therefore improve pulmonary diseases with airway hypersecretion though this mechanism." (PMID 36768212, 2023).
squamous cell carcinoma (3 papers, 2013 to 2023). A carcinoma arising from squamous epithelial cells. "It was interesting to observe that higher expression of AQP5 was noted in adenocarcinoma than in squamous cell carcinoma (68.0% vs 28.6%)." (PMID 36766810, 2023). "We searched for markers which can specifically detect this CK5/IVL double-negative population and focused on aquaporin-5 (AQP5) which is expressed in normal epidermis and epithelial cells of airways, and in squamous cell carcinoma of the oral cavity." (PMID 34934075, 2021).
type 1 diabetes (3 papers, 2016 to 2024). "It is noteworthy that maternal type 1 diabetes induced postnatal changes in the development of rat SG in offspring, including decreased AQP5 expression." (PMID 32630469, 2020). "Although type 1 diabetes in rat and mouse animal models displays reduced saliva production, divergent data exist concerning a modification in AQP5 expression, localization and muscarinic agonist-induced translocation." (PMID 32630469, 2020). "Indeed, in rats with streptozotocin-induced type-1 diabetes, as well as in senescent rats, cevimeline injection restored AQP5 trafficking." (PMID 26828482, 2016). "In this study, our experiments confirmed that type 1 diabetes results in decreased tear fluid and decreased corneal sensitivity, with dysregulation in the lacrimal functional unit (i.e., decreases in lacrimal gland number and aquaporin 5 secretion, and number of conjunctival goblet cells)." (PMID 38756167, 2024). "Reduced saliva flow without altered AQP5 localization was observed in mice and rats with streptozotocin-induced type-1 diabetes." (PMID 26828482, 2016).
adenovirus infection (2 papers, 2022 to 2024). "For instance, PRRSV and adenovirus infection could lead to the downregulation of AQP5, hindering water clearance and edema resolution, and causing abnormal fluid flux during pulmonary inflammation in infected animals." (PMID 38380102, 2024).
airway hyperresponsiveness (2 papers, 2017 to 2024). "It is a reasonable hypothesis that the downregulation of AQP5 is closely linked to airway hyperresponsiveness." (PMID 39440058, 2024). "In addition, AQP5 was one of the targeted genes leading to the airway hyperresponsiveness." (PMID 28630635, 2017).
autosomal dominant congenital cataract (2 papers, 2022 to 2023). "Recently, mutations in AQP5 have been directly related to the development of autosomal dominant congenital cataracts." (PMID 37511188, 2023).
benign breast tumor (2 papers, 2011 to 2015). "In the tissue sections of benign breast tumor, immunoperoxidase labeling of AQP5 was exclusively associated with ductal epithelial cells." (PMID 22145049, 2011).
cataract (2 papers, 2023). Partial or complete opacity of the crystalline lens of one or both eyes that decreases visual acuity and eventually results in blindness. "In conclusion, WES was performed on 20 families with pediatric cataracts, reaching a diagnosis rate of 10%, in which two known mutations were found in the AQP5 gene (OMIM 600442) and in the 2q37 locus." (PMID 37511188, 2023).
CMV infection (2 papers, 2019 to 2021). "This study shows that the C-allele of the AQP5 −1364/A/C single nucleotide promoter polymorphism is associated with a marked increase in CMV infection and CMV disease risk in the first year after kidney transplantation." (PMID 31867018, 2019). "Multivariate Cox regression analysis revealed the AQP5 −1364A/C genotype was both an independent and strong (due to the estimated effect size) risk factor for CMV infection." (PMID 31867018, 2019). "Additional studies, especially to uncover mechanistic insights, are needed to further asses the effect of AQP5 expression on inflammation and immune cell migration, as it relates to CMV infection risk." (PMID 31867018, 2019). "During opportunistic CMV infections attributed to immunosuppression after kidney transplantation, the C-allele of the AQP5 −1364A/C promoter polymorphism is independently associated with an increased 12-months infection risk." (PMID 31867018, 2019). "One-year CMV infection risk was significantly associated with the AQP5 −1364A/C genotypes (p = 0.001)." (PMID 31867018, 2019). "Taken together, this AQP5 polymorphism could contribute to the risk of CMV infection in kidney transplant recipients due to an altered resistance to viral infections, but data addressing this topic are completely lacking." (PMID 31867018, 2019). "Furthermore, multivariable COX regression revealed the C-allele of the AQP5 −1364A/C polymorphism to be a strong and independent risk factor for cytomegalovirus infection." (PMID 31867018, 2019). "Accordingly, we tested the hypothesis that the AQP5 promoter −1364A/C polymorphism is associated with the risk of CMV infection in kidney transplantation recipients." (PMID 31867018, 2019). "Accordingly, we tested the hypothesis that the AQP5 promoter −1364A/C polymorphism is associated with the risk of cytomegalovirus infection in kidney transplantation recipients." (PMID 31867018, 2019). "These hypotheses are in line with our results demonstrating that AC/CC genotypes of the AQP5 −1364A/C SNP are strong and independent risk factors of CMV infection, as compared to the risk with AA genotypes." (PMID 31867018, 2019). "Thus, the AA-genotype of the AQP5 genotype seems likely to be associated with better neutrophil granulocyte reactivity, which could at least in part explain the lower risk of CMV infection described by this study." (PMID 31867018, 2019). "Considering these results, it can be suggested that the AQP5 −1364A/C promoter SNP critically shapes the innate and adaptive immune response in response to CMV infections." (PMID 31867018, 2019).
COVID-19 (2 papers, 2021 to 2022). A disease caused by infection with severe acute respiratory syndrome coronavirus 2. "Therefore, AQP-5 may be a promising drug target for treating abnormal humoral metabolism as well as lung injury caused by COVID-19." (PMID 34163357, 2021). "AQP5 expression is also regulated by inflammatory cytokines, and the elevated level of TNF-α decreases AQP5 expression in mice, which has a high volume in inflammatory respiratory diseases such as COVID-19." (PMID 36232935, 2022). "There is some information about COVID-19 linkage with AQP5 and TRPV4 channels." (PMID 36232935, 2022). "The expression of AQP-5 is regulated by inflammatory cytokines, like TNF-α, elevated in the plasma of critical COVID-19 patients." (PMID 34163357, 2021).
diffuse palmoplantar keratoderma (2 papers, 2022 to 2025). Palmoplantar keratoderma that diffusely involves most of the palm and sole and is caused by a genetic abnormality. "A genetic diagnosis was found in a comparable percentage in patients with diffuse PPK, despite the presence of founder variants in SERPINB7 and AQP5 in the Finnish patients." (PMID 39630431, 2025).
endolymphatic hydrops (2 papers, 2012 to 2015). An accumulation of endolymph in the inner ear (labyrinth) leading to buildup of pressure and distortion of intralabyrinthine structures, such as cochlea and semicircular canals. "Therefore, failure in the human cochlear AQP4/AQP5–water shunt could contribute to impaired endolymph volume homeostasis, e.g., leading to the endolymphatic hydrops in Ménière’s disease." (PMID 26208470, 2015).
esophageal cancer (2 papers, 2020 to 2022). A primary or metastatic malignant neoplasm involving the esophagus. "Overexpression of AQP1 and AQP5 was associated with poor prognosis in lung and esophageal cancers and soft tissue sarcomas." (PMID 32075009, 2020). "In esophageal cancer, the expression levels of AQP3 and AQP5 are significantly higher compared with those in adjacent normal tissues." (PMID 35068345, 2022).
gastric adenocarcinoma (2 papers, 2016 to 2020). "AQP-3 and AQP-5 promote migration and proliferation of gastric adenocarcinoma cells." (PMID 33209198, 2020). "The increased expression of AQP5 may indicate its role in the cell differentiation of human gastric adenocarcinomas." (PMID 27589719, 2016).
glaucoma (2 papers, 2023 to 2024). Increased pressure in the eyeball due to obstruction of the outflow of aqueous humor. "Prioritized gene variants in our glaucoma case-control cohort supported possible causal roles in four genes for POAG (AQP5, FOXM1, SRFBP1 and CDH6) and three genes in PACG (LAMA2, ACACB and RGL3)." (PMID 36833422, 2023). "Rare, deleterious SNVs in AQP5, SRFBP1, CDH6 and FOXM1 from POAG families and in ACACB, RGL3 and LAMA2 from PACG families were found exclusively in glaucoma cases." (PMID 36833422, 2023). "AQP5, SRFBP1 and CDH6 also revealed significant altered expression in glaucoma in expression datasets." (PMID 36833422, 2023). "We identified multiple genes of interest with higher relative expression in glaucoma-related cell types; examples include NEFM, SYT2 expression in RGCs, AQP5 and KRT3 expression in corneal epithelial cells and CDH6 in ciliary muscle." (PMID 36833422, 2023). "We identified rare, possibly pathogenic variations in AQP5, FOXM1, SRFBP1 and ACACB in the sporadic glaucoma cases that were not present in the families." (PMID 36833422, 2023).